IRS1 (insulin receptor substrate 1)
Diseases named in the same sentence as IRS1 in open-access papers (continued):
Sharing a sentence is not in itself a finding about the gene and the disease.
Insulin resistance (continued). "Furthermore, magnesium deficiency also impairs insulin signaling, which may contribute to insulin resistance by disrupting certain key pathways, such as the insulin receptor substrate-1, its interaction with phosphatidyl-inositol 3 kinase, and reduced Akt phosphorylation." (PMID 41010443, 2025). "Viscosol improved insulin resistance by significantly up regulating INSR, IRS1, PI3K, andGLUT4 expression at both transcriptional and translational levels." (PMID 40173145, 2025). "For instance, when rat skeletal muscle myotubes are exposed to testosterone for 16 h, they exhibit increased insulin-induced serine phosphorylation of IRS-1, which is thought to uncouple IRS-1 signal transduction to PI3K, and thus result in insulin resistance." (PMID 40013621, 2025). "Sustained ER stress ultimately promotes insulin resistance, exemplified by activation of JNK, which phosphorylates IRS-1 and disrupts insulin signaling." (PMID 41226411, 2025). "It not only improves glycemic control via PI3K/Akt and IRS1 restoration, but also blocks NF-κB-mediated inflammation, decreasing expression of TNF-α and IL-6—two upstream drivers of adipose and hepatic insulin resistance." (PMID 40981178, 2025). "PTP1B plays an important physiological role in the negative modulation of insulin sensitivity by dephosphorylating IRS1 and increases in PTP1B activity have been reported to be involved in the pathogenesis of insulin resistance and diabetes." (PMID 39422717, 2025). "TNF-α promotes inflammation and insulin resistance by influencing the MAPK and NF-κB signaling pathways and IRS-1 phosphorylation." (PMID 40362446, 2025). "O-GlcNAcylation of insulin receptor substrate 1 (IRS-1) has been shown to impair AKT signaling, thereby contributing to the development of insulin resistance." (PMID 41373704, 2025). "ECG also functioned against the actions of OA via induction of p-Tyr-IRS-1/PKB/GSK3β pathway, subsequently reducing the insulin resistance by scavenging ROS and targeting AMPK." (PMID 40806739, 2025). "Upon entry, these cargo components IRS1/2, PI3K regulatory subunits (p85α), and the translocation of AKT–AS160–GLUT4, exacerbating ovarian insulin resistance." (PMID 41010046, 2025). "In particular, STZ-induced insulin resistance in astrocytes reduces endogenous neurotrophic factor expression, including GDNF, and disrupts the IR/IRS-1/Akt signaling pathway, which is part of the downstream cascade activated by GDNF through RET." (PMID 40456763, 2025). "Knockout of SARM1 in mice leads to a significant activation of insulin resistance-related pathways including AKT, GSK3β, IRS1, and FOXO1, thereby alleviating insulin resistance in mice fed a high-fat diet." (PMID 39021599, 2024). "For example, the O-GlcNAcylation of insulin receptor substrate 1 (IRS-1) hindered the functioning of AKT, leading to the onset of insulin resistance." (PMID 38540730, 2024). "In patients with insulin resistance, the adipokines resistin, leptin, PAI-1, and retinol binding protein 4 (RBP4) can dysregulate the insulin receptor substrate-1 (IRS-1) level in megakaryocytes, thus disrupting insulin signaling in platelets." (PMID 38672744, 2024). "TNF-α is thought to reduce insulin signaling by decreasing the phosphorylation of the insulin receptor substrate-1 (IRS-1) Tyr632 and Akt Ser473, which are downstream effectors of the insulin receptor, thereby resulting in insulin resistance." (PMID 39200235, 2024). "There is evidence that liver cells exposed to high levels of glucose, fructose, or sucrose induce insulin resistance in rodents, Consequently, insulin receptor signaling could be suppressed by decreased insulin receptor expression or increased phosphorylation of insulin receptor substrate 1 (IRS-1)." (PMID 38323033, 2024). "This hyperactivation phosphorylates and inhibits insulin receptor substrate 1 (IRS-1), thus blunting insulin signalling and contributing to insulin resistance." (PMID 39007094, 2024).
Insulin resistance (continued). "Methylation of PRKCZ in the underfed group negatively correlated with INSR and IRS1 expression, and positively with CRP, showing a relationship between methylation and inflammatory and insulin resistance markers." (PMID 38256201, 2024). "Increased DAG levels inhibit PKC, leading to defective activation of IRS-1/PI3K/AKT insulin signaling, downregulation of GLUT4 and forthcoming insulin resistance." (PMID 39728000, 2024). "In conclusion, our findings indicate that insulin induces insulin resistance in human DPSCs, resulting in impairments in proximal insulin signaling events (INSR, IGF1R, IRS1, and PI3K) while maintaining the activity of distal pathway components (AKT and mTOR)." (PMID 39075596, 2024). "Silybin has the capacity to transfer the phosphate group from JNK to Insulin receptor substrate 1 (IRS1), and the subsequently, IRS1 bearing phosphate group can counteract insulin resistance to ameliorate NASH." (PMID 38368351, 2024). "MAPKs are significantly altered in insulin resistance and ERK1/2 regulates IRS-1 phosphorylation at Ser612." (PMID 38883605, 2024). "These inflammatory factors can lead to the degradation of insulin receptor substrate 1 (IRS1) in the liver, reducing insulin sensitivity, ultimately leading to the development of insulin resistance and elevated blood glucose levels." (PMID 39728311, 2024). "Activation of NF-κB inhibits the IRS-1/PI3K/AKT/GLUT4 pathway, impels oxidative energy supply, and aggravates insulin resistance." (PMID 40302954, 2024). "Multiple markers like phosphorylated insulin receptor substrate 1(p-IRS), protein kinase B (p-Akt) and phosphorylated glycogen synthase kinase-3 beta (p-GSK3β) are quantified for the insulin resistance and diabetes mellitus in this study." (PMID 39281480, 2024). "In mouse and differentiated skeletal muscle cell culture models of insulin resistance, SMTNL1 can attenuate the effects of altered IRS-1 serine phosphorylation induced by the over-activation of Ser/Thr protein kinases." (PMID 38883605, 2024). "One of the signaling pathways involved in the inflammatory mechanisms is the activation of JNK1 by TNF-α, which results in serine phosphorylation of insulin receptor substrate 1 (IRS1) and impairs insulin signaling and subsequent insulin resistance." (PMID 39065815, 2024). "It is known that activation of inflammatory pathways via serine kinase phosphorylation of IRS1 and IRS2 establishes a link between inflammation and insulin resistance." (PMID 39268230, 2024). "Further, it improves liver insulin resistance in db/db mice and alleviates T2DM by regulating IRS1/PI3K/AKT/GSK3β signaling pathway." (PMID 38799166, 2024). "For instance, the binding between HDAC2 and insulin receptor substrate-1 (IRS-1) can impair insulin receptor-mediated tyrosine phosphorylation, leading to insulin resistance." (PMID 39596347, 2024). "Additionally, DPHC could regulate glucose metabolism and hypoglycemic activity well in both db/db mouse models and in vitro high-glucose induced IR-HepG2 cells, and its mechanism improves insulin resistance by regulating IRS1/PI3K/AKT/GLUT4 signaling pathway, showing potential for T2DM treatment." (PMID 38799166, 2024). "Key findings include the disruption of insulin signaling pathways due to aberrant phosphorylation of IRS-1 and IRS-2, resulting in impaired glucose uptake and insulin resistance." (PMID 39519193, 2024). "Meanwhile, FoxO1‐dependent downregulation of IRS1 led to reduced AKT signalling and insulin resistance." (PMID 38494853, 2024). "Excessive Aβ inhibits the insulin binding ability of InsRs to some extent, and this further exacerbates insulin resistance by activating JNK/TNF-α pathways and inducing IRS-1 phosphorylation." (PMID 38818523, 2024). "IRF3 knockout reduced the phosphorylation of residue Tyr608 in insulin receptor substrate 1 (IRS1) and the phosphorylation of protein kinase B (AKT) in the livers of HFD-fed mice, further aggravating HOMA-IR and insulin resistance." (PMID 38164186, 2024).
Insulin resistance (continued). "This serine phosphorylation of IRS-1 by JNK and IKK is a critical molecular event linking inflammation to insulin resistance." (PMID 39519193, 2024). "Due to hyperinsulinemia in NAFLD, de novo lipogenesis and insulin resistance can be induced via upregulation of SREBP-1c and inhibition of insulin receptors through reduced expression and sensitivity of IRS1/2." (PMID 38504356, 2024). "These downstream effectors can mediate insulin resistance directly by downregulating GLUT4 and insulin receptor expression, promoting serine phosphorylation of insulin receptor substrate (IRS-1), or indirectly by inducing inflammatory factors and ROS51." (PMID 38704482, 2024). "A previous study reported that increasing levels of TNFα and IL1β impairs the phosphorylation of IRS1/2 via severe mechanisms (MAPK, JNK and IKK) in obesity, resulting in insulin resistance in liver and adipose tissues." (PMID 38338579, 2024). "Hyperuricemia elevates the phosphorylation of insulin receptor substrate 1 (IRS1) and inhibits phosphorylation of Akt, while elevated levels of reactive oxygen species (ROS) can induce insulin resistance." (PMID 38704549, 2024). "Specifically, signaling via the Mtorc1 pathway promotes the serine phosphorylation of IRS-1 (p-IRS-1), a known marker of insulin resistance." (PMID 38257161, 2024). "Other targets of this miRNA are the genes Insulin Receptor Substrate 1 and 2 (IRS1/IRS2) and Insulin-Like Growth Factor 1 (IGF-1), which are closely related to insulin resistance, a characteristic condition of diabetes." (PMID 37511739, 2023). "IFN-γ has been reported to induce insulin resistance by activating STAT1 in adipocytes, decreasing the phosphorylation of the serine/threonine kinase, and downregulating insulin receptor substrate 1 and glucose transporter type 4." (PMID 37110462, 2023). "In the insulin resistance state, there is a disruption in the Protein Kinase B (Akt)/Phosphoinositide 3-kinase (PI3K)/Insulin receptor substrate 1 (IRS-1) signaling pathway as an insulin response pathway." (PMID 37508403, 2023). "Ubiquitin-mediated degradation of IRS1 and IRS2 is another mechanism which promote cytokine induced insulin resistance and have contribution in diabetes as well as in β cells dysfunctioning." (PMID 37014444, 2023). "It has previously been shown that a polyphenol named silibinin prevented IRS-1/PI3K/Akt inhibition in C2C12 myotubes, hence preventing insulin resistance induced by palmitate." (PMID 37298440, 2023). "Further upregulation of IRS-1, SIRT1, GLUT-4 and downregulation of ADAM17, demonstrated its potential impact on glucose homeostasis, insulin resistance and chronic inflammatory markers." (PMID 37089941, 2023). "TNFα negatively affects insulin signaling by attenuating the insulin-stimulated tyrosine phosphorylation of the insulin receptor and insulin receptor substrate 1 (IRS1) in the WAT and muscles, leading to insulin resistance." (PMID 37755259, 2023). "Homogeneous polysaccharides from Sargassum pallidum ameliorate insulin resistance by upregulation of PI3K, Glycogen synthase (GS), and IRS-1 expression in insulin-resistant HepG2 cells." (PMID 36627919, 2023). "Inflammatory cytokine and ER stress phosphorylates serine of IRS-1 (serine 302 and serine 307), which inhibits IRS activity and results in insulin resistance." (PMID 36834911, 2023). "Increased BCAA leads to mitochondrial dysfunction and sustained activation of the mTOR signaling pathway, which increases Ser phosphorylation of IRS-1 and inhibits the GLUT4 transport of glucose, ultimately leading to insulin resistance." (PMID 37686185, 2023). "The accumulated lipids activate the serine/threonine cascade, which subsequently inhibits GLUT4 translocation and insulin receptor substrate 1 (IRS1), leading to lipid-induced insulin resistance and finally cardiac dysfunction." (PMID 37685995, 2023).
Insulin resistance (continued). "Obese individuals have a higher serum level of IL-6, which is correlated with the development of metabolic syndrome, insulin resistance, and T2DM due to the capability of IL-6 to downregulate the gene expression of GLUT-4 and IRS-1." (PMID 37576807, 2023). "In both cases, insulin receptor substrate-1 (IRS-1) phosphorylation inhibits insulin signaling and promotes insulin resistance." (PMID 37372020, 2023). "FFAs are other factors involved in the induction of hepatic insulin resistance via several mechanisms, including PKC-δ, phosphorylation of Akt, IRS-1, insulin receptor, and de novo lipogenesis." (PMID 37876013, 2023). "HMGB1 accelerates insulin resistance by increasing the expression of RAGE, activating the TLR4/JNK/NF-κB pathway and reducing activation of the IRS-1 signaling pathway." (PMID 37065747, 2023). "In this study, we focus on miR-128a, which is known to negatively regulate the IRS1/AKT axis, thus promoting insulin resistance." (PMID 37047241, 2023). "Further the downregulation of IRS-1, SIRT1 and GLUT-4 and upregulation of ADAM 17 demonstrates its potential impact on glucose homeostasis, insulin resistance and chronic inflammatory markers." (PMID 37089941, 2023). "Mice with knocked-out IRS-1 and IRS-2 genes in the liver exhibited significant signs of hyperglycemia, hyperinsulinemia, hyperlipidemia, and insulin resistance." (PMID 37108143, 2023). "Estradiol induced insulin resistance via membrane estrogen receptor (ER)-mediated activation of JNK and subsequent serine phosphorylation of IRS-1." (PMID 36631877, 2023). "Studies have shown that serine phosphorylation of IRS-1 (Ser636/639 and Ser307) results in an impaired insulin/PI3K/Akt signaling pathway and increased insulin resistance." (PMID 36982168, 2023). "On its hand, IL-1β further promotes insulin resistance, triggering TNF-α production and decreasing the phosphorylation of IRS-1, also contributing to β-cell failure and diabetes progression." (PMID 37299482, 2023). "The phosphorylation of IRS-1ser307 is related to decreased IRS-1-tyrosine (IRS-1tyr), phosphorylation, and insulin resistance." (PMID 36145191, 2022). "Decreases IRS-1 activation and AKT-induced glucose uptake, as well as exacerbates systemic insulin resistance and the development of T2DM." (PMID 36451736, 2022). "High concentrations of palmitic acid can enhance serine 307 phosphorylation of insulin receptor substrate 1 (IRS1) through multiple mechanisms, leading to insulin resistance." (PMID 36238598, 2022). "Consistent with their protection from age-related insulin resistance, aged HF-fed 11β-HSD1 KO mice had similar mRNA expression levels of both IRS1 and PI3K-p85 to that of young HF-fed controls." (PMID 36205523, 2022). "To verify the improvement effect of HIIT on insulin resistance in T2DM mice, we detected the mRNA and protein expression levels of IRS1/PI3K/AKT, and the results were consistent with our expectations." (PMID 36676939, 2022). "In fact, several studies used the protein expressions of IRS-1 and GLUT4 to determine the insulin signalling related to insulin resistance." (PMID 36235772, 2022). "Hence our results suggest IRS-1 Gly792Arg polymorphism may exert its effect on the phenotypic expression in PCOS by having protective functions in case of hirsutism or may lead to an increase in the risk of adiposity and insulin resistance." (PMID 36011374, 2022). "These cytokines further promote serine phosphorylation of insulin receptor substrate-1 (IRS-1) to dampen insulin signaling, ultimately inducing insulin resistance." (PMID 36091068, 2022). "As a bridge between inflammation and insulin, inflammatory factors promote the phosphorylation of IRS-1 at the Ser307 site by activating JNK phosphorylation, thereby hindering insulin signaling and exacerbating insulin resistance." (PMID 35745162, 2022).
Insulin resistance (continued). "IRS-1 and IRS-2 regulate insulin-dependent hepatic glucose metabolism, and their dysregulation contributes to insulin resistance and type 2 diabetes." (PMID 36290594, 2022). "This, in turn, lowers the expression of insulin receptor substrate 1 (IRS-1) and glucose transporter type 4 (GLUT4) and leads to the development of insulin resistance." (PMID 36232443, 2022). "IRS-1 and IRS-2 are downstream signal factors of InsR, and those are the critical kinase of glucose uptake and the target of insulin resistance." (PMID 35845787, 2022). "In contrast, TLB markedly mitigated insulin resistance in KK-Ay mice by reversing the changes of GLUT-2, p-IRS-1, p-Akt, and p-GSK-3β." (PMID 35153796, 2022). "These kinases will mediate insulin resistance directly by downregulating insulin receptor expression, impair IRS-1 tyrosine phosphorylation, promote IRS-1 serine phosphorylation, leading to defective insulin receptor signaling." (PMID 35454131, 2022). "In recent studies, it has been proved that the reduction of insulin receptor substrate 1 (IRS-1) and Kinase B (PKB/Akt) plays a vital role regarding the origin pathomechanism of insulin resistance in patients with HCV is concerned." (PMID 35054072, 2022). "Aldosterone promotes insulin resistance via increased insulin-like growth factor (IGF)-1 receptor expression and hybridization with IRS-1, in addition to mediating Ang II-stimulated ERK1/2 phosphorylation in vascular smooth muscle cells." (PMID 35055038, 2022). "Hyperglycemic-induced oxidative stress triggers serine-threonine kinases such as IKKβ that sequentially phosphorylate IR and IRS-1 and in succession downregulate PI3K initiation to instigate insulin resistance." (PMID 36235831, 2022). "It has been proposed that decreased tyrosine phosphorylation of IRS-1 and increased phosphorylation of IRS-2 Ser 312 are the molecular mechanisms of insulin resistance among PCOS patients." (PMID 35327342, 2022). "We determined altered levels of IRS-1, tyrosine phosphorylation, and serine-632 phosphorylation of IRS-1 in the gastrocnemius muscle of OZRs, mostly considered to be a marker of insulin resistance for obesity and type 2 diabetes." (PMID 36547071, 2022). "The function of two key targets of insulin action, glycogen synthase and insulin receptor substrate-1 (IRS1), is suppressed by GSK-3, making it a promising drug target for treatment of insulin resistance and diseases of glucose metabolism (e.g., diabetes)." (PMID 35159367, 2022). "It is important to mention that a decrease in IRS1 and IRS2 with an accompanying activation in Foxo1 is also present in the heart of animals with DM type 2 or insulin resistance." (PMID 35454166, 2022). "Among inflammatory mediators, TNF-α and interleukin-1β (IL-1β) have been reported to mediate insulin resistance by IKKβ and JNK1-induced IRS-1 serine phosphorylation." (PMID 35327570, 2022). "Among them, it has been reported that serine phosphorylation of IRS-1, an insulin resistance indicator induced by insulin-resistant inducers such as JNK and IKKβ, is critical to developing insulin resistance." (PMID 36145191, 2022). "Therefore, different sites of IRS-1 may involve in the brain insulin resistance in diabetic rats." (PMID 34149862, 2021). "First, we provide new evidence for the increased serine phosphorylation levels of IRS1 (Ser307) and IRS2 (Ser731) as molecular mechanism of insulin resistance observed in the bladder mucosa of FFRs." (PMID 33859259, 2021). "DAG induces insulin resistance via protein kinase C (PKC) signaling, which inhibits insulin receptor substrate 1 (IRS-1) phosphorylation." (PMID 33809061, 2021). "For example, increased O-GlcNAc modification of insulin receptor substrate 1 (IRS-1) and the kinase ATK results in less phosphorylation of these proteins and insulin resistance." (PMID 34019870, 2021).